INS (insulin)
Diseases named in the same sentence as INS in open-access papers (continued):
Sharing a sentence is not in itself a finding about the gene and the disease.
Hyperglycemia (continued). "Reversal of hyperglycemia by exogenous insulin may delay or attenuate but never eliminate the risk for developing secondary complications." (PMID 23662125, 2013). "In the present study, the effects of hyperglycemia, induced by experimental type 1 and type 2 diabetes on the structural changes of the adrenal cortex, the levels of blood biochemical factors, as well as cortisol and insulin in male Wistar rat have been studied." (PMID 23497689, 2013). "Interestingly, increased UCP-2 activity results in defective glucose-induced insulin release from pancreatic beta-cells, which could explain the apparent hyperglycemia during hibernation." (PMID 24039826, 2013). "The finding that “stress hyperglycemia,” a clinical phenomenon observed in pet cats presenting to veterinarians for treatment, is caused by enhanced hepatic glucose output, rather than insulin resistance as previously postulated, underscores the gluconeogenic potential of the feline liver." (PMID 24348462, 2013). "Moreover, low dose STZ induced hyperglycemia in rats where it defects the secretion of insulin." (PMID 23762147, 2013). "However, our recent data suggest that pancreatic insulin production in response to hyperglycemia may be a key determinant of survival in animal models of sepsis." (PMID 23826335, 2013). "The use of immunosuppressive drugs as a conditioning regimen prior to HSC transplantation may have contributed to alleviate the autoimmune reaction and achieve improvement in the levels of insulin, hyperglycemia, and the levels of C-peptide in diabetic patients." (PMID 23762531, 2013). "However, our data highlight a striking interaction at the level of the pancreas whereby the insults combine to impede early phase insulin secretion to a level inappropriate for the degree of hyperglycemia, a finding we have previously identified as being critical for survival in endotoxemic mice." (PMID 23826335, 2013). "However, the cardioprotective effect of insulin may be overshadowed by the detrimental effect of hyperglycemia." (PMID 24371503, 2013). "Study in pancreas showed that NNATα and NNATβ increased insulin secretion in the low glucose charge; under chronic high glucose conditions, the ratio of NNATβ to NNATα increased in murine pancreatic β-cells, which increased hyperglycemia-induced apoptosis by inhibition of proteasome function." (PMID 22937033, 2012). "Prevention of hyperglycaemia-induced dysfunction in cellular systems that allow insulin-independent glucose uptake, like central and peripheral nervous system, endothelial, epithelial and immune cells, would explain some of the protective effects of insulin therapy in critically ill patients." (PMID 22870170, 2012). "Therefore, downregulation of NeuroD in chronic hyperglycemia may not only decrease insulin transcription but also attenuate insulin secretion by affecting the glucose sensing and insulin exocytosis machinery." (PMID 22509362, 2012). "Acute stress hyperglycemia, the typical reaction to stress, took place in the acute period of the burn injury (first one-three days, so-called “ebb phase”) and during sepsis as well when endocrine changes characterized by an unbalanced shift between insulin and counter-regulatory hormones occurred." (PMID 23056354, 2012). "This was proposed on the grounds that fructose might be less harmful than sucrose or glucose because, unlike glucose, it causes little hyperglycemia after eating (postprandial hyperglygemia), and is metabolized independently of insulin." (PMID 22613805, 2012). "Moreover, hyperglycemia was shown to inhibit insulin action as a result of serine phosphorylation of IRS through a PKC-mediated mechanism, which may in turn increase the degradation of IRS proteins." (PMID 22662132, 2012). "However, because manual calculation of insulin boluses is both complex and time consuming, people may rely on empirical estimates, which can result in persistent hypoglycaemia and/or hyperglycaemia." (PMID 23062116, 2012).
Hyperglycemia (continued). "Since hyperglycemia- and hyperlipidemia-induced reactive oxygen species is one of the major contributors of insulin resistance, the identification of antioxidant foods, which can improve insulin sensitivity, is crucial for the amelioration of type 2 diabetes and its complications." (PMID 23145054, 2012). "As described in the study with rapamycin and Akt inhibitor, GSK690693, inhibition of the mTOR pathway may increase insulin resistance and possibly reduce β-cell function, necessitating vigilant glucose monitoring and active intervention to control hyperglycaemia." (PMID 22343617, 2012). "Hyperglycemia during ACS was thought to be “stress hyperglycemia”, which develops due to a highly complex interplay between hormones (such as catecholamines, growth hormones, and cortisol) and cytokines, ultimately leading to excessive hepatic glucose production and insulin resistance." (PMID 23270530, 2012). "Therefore, insulin might preferentially induce myocardial steatosis in the presence of hyperglycemia." (PMID 23226508, 2012). "In addition, even unrescued groups of mice from hBMSCs-VEGF and hBMSCs-PDX1 with persistent hyperglycemia showed significantly higher levels of total serum insulin and number of endogenous β-cells compared with other groups resulting in overall better clinical outcomes." (PMID 22879915, 2012). "Thus, insulin is needed for hyperglycemia to inhibit gastric glucagon secretion." (PMID 22969729, 2012). "Insulin use may be a proxy for uncontrollable hyperglycemia with more severe disease." (PMID 22571603, 2012). "The few existent prospective human studies use non-naturalistic experimental diet paradigms that cause rapid weight gain, but also hyperglycemia, and are therefore not optimal to elucidate the physiological mechanism behind gradual weight gain leading to insulin resistance." (PMID 22682228, 2012). "This phenomenon could be associated to IR in peripheral tissues with relatively insufficient secretion of insulin, resulting in pancreatic β-cell dysfunction with severity and progress of the disease/due to the blunting effects of hyperglycemia, or by feedback suppression for a prevailing HI." (PMID 23144726, 2012). "The change in the peak insulin time point in chicory-NIA/STZ compared to NIA/STZ (60 min vs. 90 min) is an indication of a quicker response of the pancreatic beta cells to postprandial hyperglycemia and further supports chicory’s ability to stimulate insulin secretion form pancreatic beta cells." (PMID 23352214, 2012). "We believe that at this stage hyperglycemia is due to both the high glucose production accompanied by hypercortisolemia and low glucose utilization because of a lack of oxygen delivery and insulin resistance; this phenomenon is evidently associated with an adaptive mechanism for survival." (PMID 23056354, 2012). "Because such a pattern of hyperglycaemia might be expected to determine different approaches to oral agent and insulin therapy, we disaggregated Japanese data before further analysis of the determinants of the type of insulin therapy." (PMID 22519930, 2012). "Thus, because hyperglycemia has been shown to alter both insulin responsiveness in skeletal muscle and GLP-1 responsiveness in the pancreas it is essential that GLP-1 mediated glucose uptake in a cell culture model is characterized in both normal and high glucose levels." (PMID 22937169, 2012). "Aspartame exposure may promote hyperglycemia and insulin intolerance." (PMID 22697049, 2012). "As triterpenoids can acutely activate AMPK and promote fat oxidation, one plausible mechanism of the sustained efficacy to reduce hyperglycemia in the present study could conceivably be due to improved insulin action as a result of reduced lipid accumulation in muscle and liver." (PMID 22860063, 2012).
Hyperglycemia (continued). "However, patients who were subsequently switched to insulin glargine perceived the frequency of hyperglycaemia while still being treated with NPH insulin to be higher compared with patients who subsequently remained on NPH insulin for the duration of the study (3.4 ± 1.5 vs. 2.9 ± 1.2; p < 0.0001)." (PMID 22340448, 2012). "More recently, comprehensive clinical implementation of a strict insulin infusion protocol for glycaemic control of cardiac surgery patients also proved ineffective when individual risk factors of patient hyperglycaemia could not be met." (PMID 22870170, 2012). "Likewise, normalizing hyperglycemia in insulin-deficient rats does not reverse spatial cognitive impairment." (PMID 21949705, 2011). "However, during the second phase of the experiment WT mice required more insulin to maintain steady state hyperglycemia relative to GhrR KO mice, reaching statistical significance at the 70 min (5.72 ± 1.40 vs 2.41 ± 0.32 ng/mL) and 90 min (6.14 ± 1.50 vs 2.90 ± 0.34 ng/mL) time points." (PMID 21211044, 2011). "Likewise, inhibition of uricase in a rat model revealed a decrease in serum insulin and hyperglycemia and rapid removal of basal insulin in in vitro secretion as well as reversing the effect of the removal of uric acid, suggesting an interference with the mechanism of insulin secretion." (PMID 22216028, 2011). "Therefore, neuronal sensitivity to hypoglycaemia and hyperglycaemia might be deeply changed in sepsis, making the effect of insulin on neuronal metabolism unpredictable." (PMID 21612615, 2011). "However, the present study also reveals that despite the clinical benefits and the recommendations of international treatment guidelines, the initiation of insulin therapy in Asia is still being delayed for too long, resulting in many patients developing severe hyperglycemia." (PMID 21631903, 2011). "In that particular study, 10% of dedifferentiated acinar cells expressed insulin, with a total insulin content of 40 to 90% of primary β-cells, and transplantation of about 100,000 of these insulin-positive cells was sufficient to revert hyperglycemia in a diabetic nude mouse model." (PMID 22007286, 2011). "Due to lack of data about the exact extent of glycemic control, we could not examine whether hyperglycemia per se or a higher dose of insulin glargine attributes to the association with a greater risk of certain specific cancer." (PMID 21738645, 2011). "Taken together, these findings strongly suggest that Men1 ablation prevents STZ-induced hyperglycemia at least in part through promoting beta-cell proliferation, resulting in the maintenance of a larger number of functional beta cells and higher circulating insulin concentrations." (PMID 21318185, 2010). "For centers that do employ a standard treatment approach, all (6/6) indicated they may use insulin infusions for glycemic control, while some also attempt to manage hyperglycemia using intermittent insulin (subcutaneous or intravenous) and/or modification of dextrose in fluids." (PMID 20128893, 2010). "The mechanism behind that adverse effect may be increased insulin resistance, uncontrolled hyperglycemia, uncontrolled nutritional supply, a triggering of the inflammatory response, and a shortage of substrates for the immune system induced by a decreased peripheral release of glutamine." (PMID 20798757, 2010). "Hyperglycemia may be due to insufficient insulin or poor response to insulin." (PMID 21042492, 2010). "Finally, blood insulin levels decrease and hyperglycemia develops." (PMID 22043204, 2010). "Thus, it is possible that normalization of hyperglycemia and improvement in insulin sensitivity may have contributed to the enhancement of exercise performance, in addition to the benefits of improved cardiac function and remodeling." (PMID 21080957, 2010). "Also, insulin may correct the deleterious effects of hyperglycemia at the cellular level of the GPx by increasing the level of nuclear factor kappa B." (PMID 20465785, 2010).
Hyperglycemia (continued). "However, chronic hyperglycemia stimulates amylin production in insulin-resistant condition." (PMID 21113299, 2010). "The induction of insulin/IGF-1-like growth signaling pathways that depend on RAS, AKT, mTOR and other oncogenic proteins has been implicated in aging and a number of age-related diseases in humans, including many for which hyperglycemia and/or excess calorie intact are risk factors." (PMID 21076178, 2010). "Given the definition of hyperglycaemia, including the use of insulin for >12 hours, one can not assume that the association is due to poorly controlled hyperglycemia in this design, but may be the effect of insulin." (PMID 20646308, 2010). "The risk factors for hyperglycemia after the pancreas transplant were associated with the type of transplant (SPKT vs PAKT and pancreas transplant alone), with type 2 diabetes vs type 1 diabetes history, with the pretansplant insulin dose and BMI, and with the acute rejection episodes occurrence." (PMID 19825194, 2009). "However, as demonstrated with troglitazone, this class of compounds, when used in subjects with impaired glucose tolerance, may improve glucose-coupled insulin secretion and reduce the level of postprandial hyperglycemia." (PMID 19402896, 2009). "In addition to alterations of the insulin/glucagon axis, the direct effect of chronic hyperglycemia may affect the expression level of PGC-1α." (PMID 19142226, 2009). "Hence, reduction of blood sugar in T2DM (where there is hyperglycemia) by GLP-1 appears to be secondary to hyperglycemia (which increases insulin secretion and decreases glucagon release) as well as due to a direct action of GLP-1 on glucagon release which is potentiated by hyperglycemia." (PMID 21264154, 2008). "However, if vinegar reduces postprandial hyperglycemia and delays gastric emptying, the doses of preprandial injections of short-acting insulin may have to be adjusted." (PMID 18093343, 2007). "The strategy is not simply that used in adult intensive care to actively titrate insulin in subjects with hyperglycaemia, although the adult outcome data particularly with respect to reductions in sepsis, with tight glycemic control, may have interesting parallels." (PMID 17692117, 2007). "Moderate hyperglycemia is a potent stimulus for β-cell differentiation and expansion in vivo and in utero, so we tested whether exposure of stage 3 cells to elevated glucose levels could induce insulin expression." (PMID 15839736, 2005). "The patient initially presented with hyperglycemia prior to admission during ICI therapy, which raised concern about new-onset type 1 diabetes due to impaired insulin secretion." (PMID 41536580, 2026). "Serum insulin and glucose significantly varied across all groups, with the PARGL group exhibiting hyperinsulinemia and persistent hyperglycemia during starvation." (PMID 41550891, 2026). "Prophylactic use of insulin sensitizers, such as metformin, can mitigate PI3K/AKT inhibitor–induced hyperglycemia." (PMID 41345397, 2025). "By improving the efficiency of insulin action, THCV addresses one of the central mechanisms that contributes to hyperglycemia and disease progression." (PMID 40270953, 2025). "This inhibits glucose-stimulated insulin secretion (GSIS), promoting the development of postprandial hyperglycaemia and eventually T2DM." (PMID 41542178, 2025). "In this study, the state of hyperglycemia in the ALX group resulted from the damage of alloxan to the β-cells, which led to the reduction in insulin secretion." (PMID 40733028, 2025). "The mechanisms of antidiabetic action of this unique class of compounds may be diverse and include: insulin-mimetic action, ability to inhibit specific enzymes (α-amylase, glucosidase, aldose reductase), antioxidant activity, and the ability to regulate hypo/hyperglycemia." (PMID 40686811, 2025).
Hyperglycemia (continued). "To model control of hyperglycemia via insulin treatment in T1DM and insulin-dependent T2DM, we administered insulin daily to the diabetic mice, and used blood sugar as a measurement of diabetic control." (PMID 39937900, 2025). "Prediabetes and T2D are marked by chronic hyperglycaemia, characterised by elevated levels of FGB, HbA1c, insulin and HOMA-IR, along with impaired β-cell function." (PMID 41280283, 2025). "We achieved a similar degree of hyperglycemia in βGRK2KO and control mice with comparable glucose infusion rates (GIR), however, insulin secretion in response to glucose was substantially reduced in βGRK2KO mice." (PMID 40054692, 2025). "Hyperglycaemia rapidly augments vascular NGF release, activates β-cell TrkA and amplifies glucose-stimulated insulin secretion (GSIS)." (PMID 41471293, 2025). "This study evaluates clinical management and pregnancy outcomes in GCK-hyperglycemia and HNF1A-MD pregnancies focusing on insulin therapy, glycemic control and neonatal outcomes." (PMID 41409604, 2025). "By suppressing appetite-driven hyperglycemia through CB1 antagonism and improving insulin sensitivity via CB2 activation, THCV provides a comprehensive approach to glycemic control." (PMID 40270953, 2025). "Isorhamnetin (ISO) alleviates hyperglycemia in STZ-induced T1DM, lowers LDL-C, increases plasma insulin (L-ISO), and preserves islet morphology (significant in L-ISO)." (PMID 41156454, 2025). "Factors such as hyperglycemia, AGEs, oxidized low-density lipoprotein (ox-LDL), and abnormal insulin expression can directly or indirectly induce endothelial dysfunction." (PMID 40093018, 2025). "The Gnasβcell–/– mice displayed ambient hyperglycemia on HFD following tamoxifen treatment and elevated fed glycemia along with reduced plasma insulin levels." (PMID 40526441, 2025). "Type-2 diabetes (T2DM) worsens cognitive decline and impairs insulin signaling in Alzheimer’s disease (AD), with both conditions involving disrupted glucose metabolism-T2DM through chronic hyperglycemia and AD through impaired neuronal glucose uptake." (PMID 40871536, 2025). "Disruption of the insulin signaling cascade—particularly the phosphoinositide 3-kinase (PI3K)/AKT pathway—leads to a cascade of metabolic disturbances, including hyperglycemia, dyslipidemia, and chronic inflammation." (PMID 40426647, 2025). "Hyperglycaemia activates the NF-κB and JNK pathways, leading to pro-inflammatory milleu, impaired insulin signalling and insulin resistance in several insulin-responsive tissues, such as hepatocytes, skeletal muscles, adipocytes and endothelial cells." (PMID 40216734, 2025). "If the patient presents with severe hyperglycemia and DKA, the oncological treatment must be stopped, and insulin therapy is mandatory." (PMID 40729244, 2025). "In 3 patients with GCK-hyperglycemia and in 1 with HNF1A-MD, insulin therapy was discontinued at the follow-up visit." (PMID 41409604, 2025). "As expected, fasting plasma glucose, glucose at 2 h post-load, triglycerides, fasting plasma insulin, insulin 2 h post-load, HbA1c, and HOMA-IR were higher in incident hyperglycemia." (PMID 40005008, 2025). "Hyperglycemia in the fasting and feeding states persist as SCD mice age and becomes accompanied by decreasing fasting serum insulin with aging and reduced islet size and β cell mass, suggesting developing pancreatic β cell dysfunction." (PMID 40294908, 2025). "On the other hand, procyanidin oligomers, isolated from black soybean, activate insulin and AMPK signaling pathways, promoting GLUT4 translocation in muscle and suppressing acute hyperglycemia." (PMID 39795230, 2025). "miR-205-5p modulates insulin sensitivity by targeting FOXO1, and its downregulation under hyperglycemia disrupts normal insulin signaling, promoting metabolic dysregulation and increased VEGFA expression." (PMID 40002404, 2025).